IRS1 (insulin receptor substrate 1)
Diseases named in the same sentence as IRS1 in open-access papers (continued):
Sharing a sentence is not in itself a finding about the gene and the disease.
Insulin resistance (continued). "Some studies have found upregulated expression of IRS1, IRS2 in PCOS patients, and the circulating Leptin levels have been directly correlated with insulin resistance, which frequently is associated with PCOS." (PMID 32038578, 2019). "TNF-α induces the phosphorylation of insulin receptor substrate 1 (IRS-1) on serine instead of tyrosine residues, promoting insulin resistance." (PMID 31331342, 2019). "It has been reported that TNF-α induced insulin resistance in skeletal muscles is attributed to the induction of IRS-1 phosphorylation on serine residue followed by the deterioration of insulin signaling." (PMID 29872751, 2018). "During insulin resistance in rodents and humans, glucose uptake mediated by IRS1 was severely impaired whereas salt reabsorption in kidney proximal tubule mediated by IRS2 was reserved." (PMID 30602666, 2018). "For example, miR-222 has been shown to be upregulated in mouse liver upon high fat/high sucrose diet +gold thioglucose; in the same study, authors showed that in primary mouse hepatocytes, miR-222 directly targets IRS1 thus inducing insulin resistance." (PMID 30469501, 2018). "The molecular mechanism by which insulin resistance is induced is through serine phosphorylation of the insulin receptor substrate 1 (IRS-1), thus impairing insulin action." (PMID 29760586, 2018). "We found the onset of insulin resistance in the liver of young rats after fructose-rich diet, as evidenced by the decreased activation of the downstream effectors of insulin receptor, IRS1 and Akt." (PMID 29755364, 2018). "The combination of p85alpha and the increase in serine phosphorylation from IRS-1 will accelerate pathogenesis of insulin resistance." (PMID 30305144, 2018). "JNK is a serine/threonine kinase shown to increase serine phosphorylation of IRS-1 and involved in insulin resistance." (PMID 30400151, 2018). "Previous studies conducted in L6 muscle cells in vitro and rat muscle in vivo have indicated that increased phosphorylation levels of Ser307 and Ser636/639 of IRS-1 leads to impairment in the insulin signaling leading to insulin resistance." (PMID 30400151, 2018). "This enzyme can destroy insulin receptor substrate 1 (IRS1) in adipocytes and hepatocytes, and in consequence induce insulin resistance and lipogenesis." (PMID 29515456, 2018). "The IRE1-XBP1 pathway contributes to the pathogenesis of insulin resistance through serine phosphorylation of insulin receptor substrate 1(IRS-1)." (PMID 30374328, 2018). "This is highlighted by our observations at 3 months of age in F2 adipose tissue displaying reduced IRS-1 and reduced pAktser473, which were both consistent with insulin resistance in this tissue." (PMID 29507362, 2018). "In vitro experiments have shown that increased exposure to elastase can contribute to IRS-1 downregulation, resulting in impaired glucose tolerance and insulin resistance." (PMID 29479350, 2018). "Later, IRS-1 pSer616 and IRS-1 pSer636/639 were identified as putative biomarkers for brain insulin resistance in AD, and were reported to correlate positively with Aβ oligomer levels and negatively with cognitive function." (PMID 30223579, 2018). "In our model, we observed that treatment with high palmitate concentrations (0.5 mM for 24 h) inhibited insulin–stimulated GLP-1 secretion and induced a state of insulin resistance at the level of the IRS-1/AKT pathway." (PMID 30487448, 2018). "These factors induce insulin resistance either by diminishing insulin receptor (IR) tyrosine kinase activity, increasing serine phosphorylation of IRS-1, or through the STAT3-SOCS3 pathway, which degrades IRS-1." (PMID 30373146, 2018). "We next directly tested the requirement for IRS1 in MitoPQ-induced insulin resistance in adipocytes and L6 myotubes." (PMID 29599292, 2018).
Insulin resistance (continued). "Firstly, ceramide inhibits insulin signaling by inhibiting insulin-stimulated phosphorylation of insulin receptor substrate-1 and blocking activation of protein kinase B, which stimulates the development of insulin resistance." (PMID 30275386, 2018). "This central insulin resistance was associated with reduced protein levels of the p110β subunit of phosphoinositide 3-kinase (PI3K) and increased serine phosphorylation of IRS-1 in the arcuate nucleus (ARC) of the hypothalamus." (PMID 30043179, 2018). "For the purpose of monitoring insulin resistance, we selected IRS-1 and GLUT4 as markers of glucose uptake ability." (PMID 30445954, 2018). "The present data demonstrated that PIO and/or MSCs improved cardiac insulin resistance through decreasing the down-regulation of cardiac IRS-1 in T2D rats." (PMID 29959408, 2018). "These modifications prevent insulin-stimulating IRS-1 tyrosine phosphorylation, which leads to insulin resistance." (PMID 29881379, 2018). "For example, TNF-α is able to induce insulin resistance by antagonizing tyrosine phosphorylation of the insulin receptor and its major cytosolic substrate, insulin receptor substrate 1 (IRS-1)." (PMID 30249998, 2018). "Due to the modulation of these inflammatory pathways, these drugs also reduced IRS-1 serine phosphorylation, a tissue marker of insulin resistance." (PMID 29760586, 2018). "A research group found that maternal diet-induced obesity leads to offspring having increased levels of MiR-126 which targets IRS1 and adipose tissue insulin resistance prior to the development of obesity, resulting in increased risk of T2D." (PMID 30602666, 2018). "Another important finding of the present study is that selective insulin resistance was demonstrated and differential contributions of IRS-1 and IRS-2 were suggested in human NAFLD subjects." (PMID 29717275, 2018). "Obese and high-fat-diet-fed mice exhibit elevated mTORC1 signaling, which is believed to be due to overdriving feedback inhibition of IRS-1 by insulin resistance." (PMID 30275871, 2018). "Acute increases in plasma FFA levels can induce insulin resistance by inhibiting glucose uptake in skeletal muscle, hepatocytes, and adipocytes, and by attenuating insulin signaling in insulin receptor substrate 1 (IRS-1) -PI3K activity." (PMID 30089498, 2018). "S6K1 is known to be a downstream effector of mTOR, and to induce insulin resistance via phosphorylation of serine residues of IRS1 as a feedback response." (PMID 29738527, 2018). "ROS have been reported to play a major role in FFA-induced insulin resistance by phosphorylating insulin receptor substrate-1 (IRS-1) in serine residue and by inhibiting the downstream insulin signaling." (PMID 29675131, 2018). "Insulin resistance can be monitored by the decreased phosphorylation of two main substrates of the insulin receptor, IRS1 and IRS2." (PMID 30024933, 2018). "Although TNF-α elicits insulin resistance in the hepatocytes, adipocytes, and activates skeletal muscle cells and phosphorylation of IRS-1 on serine residue is a common event, detailed signaling pathway is different in these cells." (PMID 29872751, 2018). "Stimulation of the rat L6 skeletal muscle cell line with recombinant leptin reduced phosphorylation of the insulin receptor substrate-1 (IRS-1) and impaired glucose uptake, suggesting that leptin promotes insulin resistance." (PMID 29760587, 2018). "Studies have shown that serine phosphorylation of IRS-1 leads to impairment in the insulin-signaling pathway and contributes to insulin resistance." (PMID 30400151, 2018). "Cardiac-specific overexpression of this molecule leads to proteasomal degradation of both insulin receptor and IRS-1 resulting in insulin resistance." (PMID 30425649, 2018). "Overexpression of IRS1 in endothelial cells restored angioblast differentiation and wound healing in HF-induced diabetic mice with insulin resistance." (PMID 30602666, 2018).
Insulin resistance (continued). "High fat-diet (HFD) produces insulin resistance in the hippocampus of mice by increasing serine-phosphorylated IRS1 (IRS1-pS616), resulting in insulin resistance." (PMID 30602666, 2018). "Treatment of C2C12 cells with METRNL markedly suppressed palmitate-induced insulin resistance, as detected by an impairment of insulin-stimulated IRS-1 and Akt phosphorylation." (PMID 30213948, 2018). "The phosphorylation of IRS-1 on serine residues is associated with insulin resistance induced by cytokines such as TNF-α, since it inhibits IRS-1 tyrosine phosphorylation leading to impaired insulin signaling." (PMID 29463262, 2018). "Simultaneously, excessive BAFF directly affects the down-regulation of IRS-1 and eventually exacerbates insulin resistance." (PMID 28630652, 2017). "In order to determine the effect of maternal obesity/high-fat diet and a postnatal high-fat diet on central insulin resistance, we assayed for the level of phospho-insulin receptor subunit-1 (IRS-1) in the dorsal hippocampus." (PMID 29340106, 2017). "InsR and IRS1 are the key proteins of the insulin signal pathway, and inhibition of mouse InsR and IRS1 activity can lead to insulin resistance in mice." (PMID 28432282, 2017). "Phosphorylation of IRS1 by IKKβ can contribute to impairment of insulin signaling pathways and to the insulin resistance mediated by inflammatory processes." (PMID 29292732, 2017). "To characterize DHTS in IRS-1/Akt signaling further, we induced insulin resistance in L6 myotubes by exposing them to dexamethasone for 24 h." (PMID 29259227, 2017). "Reduced tyrosine phosphorylation of the IRS1 protein contributes to peripheral insulin resistance and β-cell failure." (PMID 28346520, 2017). "Disturbance of the insulin signalling pathways and an increased expression of the serine-phosphorylated insulin receptor substrate 1 (IRS1-pS616), a marker of the insulin resistance, were detected in the hippocampus of the HFD mice." (PMID 28432486, 2017). "We revealed that both of these tissues from db/db mice had relatively low IRS-1 protein levels but relatively high C1-Ten levels, supporting the notion that the mechanism of insulin resistance is controlled at the point of IRS-1 levels." (PMID 29259227, 2017). "Our data showed that P300 is a prime factor leading to the development of hepatic insulin resistance by acetylating IRS1/2 in the early stages of obesity." (PMID 28743992, 2017). "Insulin resistance is induced by phosphorylation of serine residues (Ser 307/612/632) of IRS-1 by diabetes-inducing factors such as fatty acids, and TNFα." (PMID 29165364, 2017). "This activation by phosphorylating AMPK and insulin receptor substrate-1 (IRS-1) led to an improvement in insulin resistance, suppression of gluconeogenesis and an increase in mitochondrial oxidation." (PMID 28146060, 2017). "To investigate the further mechanisms of ADSC transplantation on insulin resistance, we used a q-PCR analysis method to evaluate the expression of insulin resistance-related genes, including IRβ and IRS1, as well as IRS2 and GLUT2 in the liver tissues." (PMID 29258603, 2017). "Both SOCS1 and SOCS3 have been attributed to the development of insulin resistance by inhibiting the phosphorylation of IRS1 and IRS2 proteins." (PMID 29025435, 2017). "The upregulation of SOCS1 and SOCS3 has been projected as a mechanism for imparting insulin resistance by the downregulation of IRS1." (PMID 29025435, 2017). "TNF-α via its own receptor and via activated nuclear factor kappa-light-chain-enhancer of activated B cells (NF-kB (induces serine phosphorylation of insulin receptor substrate type 1 (IRS1), Destructive insulin resistance." (PMID 29387832, 2017). "Approaches other than E3 ligase targeting are necessary to prevent insulin resistance via IRS-1 regulation." (PMID 29259227, 2017). "Inflammatory mediators promote insulin resistance through inhibitory serine phosphorylation of IRS-1." (PMID 28435687, 2017).
Insulin resistance (continued). "An experimental report has shown that PKR can phosphorylate insulin receptor substrate 1 (IRS1), which is a cellular event linked to insulin resistance in peripheral organs." (PMID 28982375, 2017). "BMP4, which is closely related to BMP2 was recently found to be upregulated in the serum of two diabetic mouse models and was proposed to contribute to insulin resistance by inhibiting IRS-1 activation and insulin signaling." (PMID 29222456, 2017). "In this study, hyperuricemic mice showed significantly increased cardiac phospho-IRS1 (Ser307) and decreased phospho-Akt levels with glucose intolerance and impaired insulin resistance." (PMID 26836389, 2016). "Recently, miR-96 was reported to be upregulated by the depletion of mitochondrial DNA and targeted IRS-1 directly in SK-Hep1 cells, suggesting that the role of miR-96 in insulin resistance results from a mitochondrial dysfunction." (PMID 28036389, 2016). "Taken together, two factors seem to be important in the pathogenesis of ‘selective insulin resistance' in the liver: both reduced Irs2 expression and intact Irs1 expression." (PMID 27708333, 2016). "In adipose tissue, IL-6 mediates inflammatory processes and causes insulin resistance by downregulating GLUT4 and IRS-1 expression." (PMID 27069930, 2016). "In insulin resistance, the adipocyte itself is enlarged and the expression of IRS1 and GLUT4 is decreased." (PMID 27247938, 2016). "High levels of BCAAs persistently activate mTORC1 (mTOR complex 1), resulting in insulin resistance through the phosphorylation of insulin receptor substrate 1 (IRS-1)." (PMID 27376324, 2016). "Elevated BCAAs stimulate mTORC1, a nutrient sensing complex, and following IRS-1 serine phosphorylation, result in insulin resistance and other metabolic disorders." (PMID 27376324, 2016). "JNK is a stress kinase that normally phosphorylates the c-Jun component of the AP-1 transcription factor and promotes insulin resistance through the phosphorylation of serine residues in insulin receptor substrate 1 (IRS-1)." (PMID 27721914, 2016). "Our results are thus in line with previous finding in that high fat diet for eight months induced insulin resistance via suppression of the phosphorylation of IRS1." (PMID 27248994, 2016). "In Alzheimer’s, neurons can become both insulin- and IGF-1-resistant, even absent the clinical diagnosis of diabetes, with elevations in IRS-1 serving as a biomarker for brain insulin-resistance." (PMID 26823968, 2016). "On the other hand, it was also demonstrated that lactate induced insulin resistance, and lactate treatment inhibited insulin action by inhibiting the insulin receptor substrate-1 (IRS-1) and IRS-2 mediated PI3K and PKB pathways." (PMID 26938239, 2016). "The characteristics of insulin resistance differ among organs and tissues; in liver IRS2-mediated pathway is impaired, causing hyperglycemia while IRS1-mediated pathway is preserved to some extent, inducing hyperlipidemia." (PMID 27247938, 2016). "Cortical levels of both IRS1 and its form phosphorylated on Serine 616 (p[S616]IRS1), which indicates insulin resistance, were also similar in P301S and WT mice." (PMID 26858121, 2016). "The total levels of IRβ and AKT were significantly decreased in APP/PS1 mice, and the levels of IRS1 pS636 and IRS1 pS612, which play a central role in insulin resistance, were significantly increased in APP/PS1 mice compared with wild‐type controls." (PMID 27457264, 2016). "Irs1 and Irs2, as also Akt2 are essential for the development of steatosis in the presence of insulin resistance." (PMID 27708333, 2016). "Plasma TNFα can cross the BBB and lead to cerebral insulin resistance by inhibiting IRS-1 phosphorylation at tyrosine residues." (PMID 27884163, 2016). "Insulin resistance is characterized by inability of insulin to exert its signaling effects, mainly due to dysfunction at the level of IRS1 and IRS2 activation and PI3K recruitment to the plasma membrane." (PMID 27434075, 2016).
Insulin resistance (continued). "On the basis of these findings, we propose that ‘selective insulin resistance' is produced as a result of predominant and intact expression of Irs1 in the PV zone, and downregulation of Irs2 expression in both the zones in the presence of hyperinsulinemia." (PMID 27708333, 2016). "Animal models and humans with insulin resistance demonstrate a reduction in the IRS1/PI3K/AKT pathway." (PMID 27676071, 2016). "Remarkably, chronic oxidative stress increased IRS-1(ser307) phosphorylation and insulin resistance whereas acute oxidative stress rescued insulin sensitivity and insulin signaling through redistribution of active cytoplasmic JNK into the nucleus." (PMID 27695421, 2016). "In this study, we found significantly increased p‐IRS1 (pS636) and p‐IRS1 (pS612) in vehicle‐treated transgenic mice; these are considered a key signature of insulin resistance." (PMID 27457264, 2016). "Phosphorylation at serine/threonine residues on IRS1 has been suggested to be a mechanism of insulin resistance by controlling IRS1 degradation and thus the ability of insulin to signal." (PMID 26956053, 2016). "TNF-α is believed to induce insulin resistance by a number of mechanisms such as increase in serine phosphorylation of IRS-1, which disrupts the insulin signaling cascade." (PMID 27379252, 2016). "Taking these results together, p38α MAPK mediates the effect of chronic insulin to promote insulin resistance by suppressing IRS1 and IRS2." (PMID 27376265, 2016). "These hormones cause the decreased phosphorylation of insulin receptor substrate-1 (IRS-1), resulting in profound insulin resistance." (PMID 27645229, 2016). "IRS-1 is involved in insulin resistance, how different glucose loading and threshold of abnormal plasma glucose levels affect the insulin resistance remained to elucidate." (PMID 27468700, 2016). "We monitored the impact of HUA on insulin resistance, insulin signaling and IR, phospho-IRS1 (Ser307) and phospho-Akt levels in myocardial tissue of an acute hyperuricemia mouse model established by potassium oxonate treatment." (PMID 26836389, 2016). "Increasing concentrations of NEFA are implicated in insulin resistance, also through effects on insulin receptor substate‐1 (IRS‐1) decrease involving IRS‐1 phosphorylation (ser307) catalysed by IKK and JNK." (PMID 26887821, 2016). "Postmortem study of AD brains indicated significant increase of insulin receptor substrate-1 (IRS-1) phosphorylation at serine residues, marker of insulin resistance." (PMID 27884163, 2016). "It has been reported that serine phosphorylation of insulin receptor-1 (IRS-1) inhibits insulin stimulated tyrosine phosphorylation of IRS-1 leading to an increase in insulin resistance." (PMID 27034691, 2016). "One theory is that an increase in BCAA levels activates the mTOR/S6K1 kinase pathway and results in the phosphorylation of several serine residues in IRS-1, contributing to insulin resistance." (PMID 27249024, 2016). "While recent studies suggested that TNF-a enhanced the insulin resistance in infection by inhibiting insulin-induced tyrosine phosphorylation of insulin receptor substrate-1(IRS-1)." (PMID 26137892, 2015). "Our data suggested that HPN suppressed insulin resistance by restoring PA-inhibited insulin signaling in HepG2 cells, including insulin-stimulated tyrosine phosphorylation of IRβ and IRS1/2 and serine phosphorylation of Akt." (PMID 26193288, 2015). "SOCS3 induces insulin resistance through increased phosphorylation of the insulin receptor on tyrosine 960, which inhibits the insulin receptor/IRS-1 interaction." (PMID 25874611, 2015). "Previously, homozygous disruption of IRS1 transcription led to mild insulin resistance, while IRS2-knockout mice exhibited severe insulin resistance." (PMID 26257839, 2015). "The overactivity of UPS and inappropriate degradation by the UPS of IRS-1 and IRS-2 was associated the development of insulin resistance." (PMID 26024304, 2015).